TREM2 (triggering receptor expressed on myeloid cells 2)
Diseases named in the same sentence as TREM2 in open-access papers (continued):
Sharing a sentence is not in itself a finding about the gene and the disease.
neurodegenerative disease (258 papers, 2013 to 2026). A disorder of the central nervous system characterized by gradual and progressive loss of neural tissue and neurologic function. "Recent studies have revealed that mutations or alterations in Trem2 are associated with the onset and progression of various neurodegenerative diseases, including AD." (PMID 40205810, 2025). "Both Thr66Met and Tyr38Cys of TREM2 were found to be associated with neurodegenerative diseases of NHD and FTD." (PMID 40806186, 2025). "TREM2 mutations were suggested to impact multiple neurodegenerative diseases, including AD, FTD, NHD, and PD." (PMID 40806186, 2025). "Although TREM2 has been implicated in neuroprotection across various neurodegenerative diseases, its specific role in PD remains to be clarified." (PMID 40393958, 2025). "It underscores the importance of structuralintegrity in maintaining signaling-competent receptor assemblies andprovides new insights for targeting TREM2 variants in the contextof neurodegenerative diseases." (PMID 41298271, 2025). "In the context of neurodegenerative diseases, TREM2 expressed on microglia is linked to prevention or downregulation of tau hyperphosphorylation and cited to harbour a protective effect in neurodegenerative disease." (PMID 39472664, 2025). "These crucial roles of TREM2 and its changes in gene expression, as well as its genetic variants, have gained significant attention from neurodegenerative disease researchers." (PMID 40309835, 2025). "TREM2 was verified as a risk factor for several neurodegenerative diseases, such as AD, FTD, NHD, and PD, suggesting a broader role in immune responses and maintaining nervous system homeostasis." (PMID 40806186, 2025). "TREM2 plays a role in neurodegenerative diseases where its elevated expression is a hallmark of disease-associated microglia, but it can also be cleaved from cell surfaces." (PMID 40641620, 2025). "TREM2 mutations involved in neurodegenerative diseases can be diverse, including single-amino-acid substitutions, frameshift mutations, nonsense mutations, and splice site-affecting variants." (PMID 40806186, 2025). "The dysfunction of TREM2 affects immune homeostasis and is closely linked to the pathogenesis of neurodegenerative diseases." (PMID 40242752, 2025). "The first identified TREM2 variants linked to neurodegenerative diseases were W78X and W44X, which cause premature protein truncation, leading to FTD or NHD pathogenicity." (PMID 40806186, 2025). "While TREM2 deletion causes fatal neurodegenerative diseases in humans, such as NHD, TREM2 knockout mice generally exhibit normal phenotypes and do not develop similar conditions." (PMID 40247363, 2025). "Multiple studies have identified TREM2 as a significant risk factor for PD, suggesting its potential as a therapeutic target for PD and other neurodegenerative diseases." (PMID 40940798, 2025). "Within the setting of neurodegenerative diseases, particularly AD, responses signaled through TREM2 trigger activation of microglia into a Damage Associated Microglia (DAM) phenotype." (PMID 39315272, 2024). "TREM2’s association with the protective roles of microglia makes it a focal point in neurodegenerative disease research." (PMID 39201760, 2024). "Triggering receptor expressed on myeloid cells-2 (TREM2) has been implicated in susceptibility to neurodegenerative disease." (PMID 38453910, 2024). "In models of neurodegenerative diseases, such as AD, microglia associated with amyloid plaques display an MGnD phenotype, characterized by activation of the TREM2-APOE pathway." (PMID 39456734, 2024). "Recently, triggering receptor expressed on myeloid cells 2 (TREM2) is identified as a crucial step in regulating lipid metabolism and associated with the pathogenesis of neurodegenerative diseases." (PMID 38145349, 2024).
neurodegenerative disease (continued). "Dysregulation of TREM2 function has been implicated in various neurodegenerative diseases, highlighting its significance in maintaining microglial homeostasis and responding to pathological stimuli." (PMID 38888203, 2024). "We then used IHC to evaluate the percentage of TREM2 fluorescence expression in the adult mice, which is a risk factor for neurodegenerative diseases and a regulator of microglial function in the brain." (PMID 38781563, 2024). "Studies in TREM2-deficient mice have elucidated its specific role in promoting microglial survival and identified a unique microglial type associated with neurodegenerative diseases." (PMID 39113887, 2024). "Exploring the genetic basis of inflammation in neurodegenerative diseases is also crucial, with recent studies linking TREM2 variants to altered microglial function in AD and HLA genes to MS susceptibility." (PMID 39539666, 2024). "Neurodegenerative diseases are closely associated with microglia, including chemotaxis, phagocytosis, and genetic variants in microglial TREM2." (PMID 37815901, 2024). "Mutations within TREM2 can be associated with age-dependent development of several neurodegenerative diseases depending on the specific variant." (PMID 36803190, 2023). "TREM2 variants are risk factors for AD and other neurodegenerative diseases (NDDs), and diverse type of TREM2 variants are associated with different NDD risk." (PMID 38020891, 2023). "For example, mutations in the triggering receptor expressed on the myeloid cells 2 (TREM2) gene, expressed by microglia, have been linked to an increased risk of AD and other neurodegenerative diseases." (PMID 38137058, 2023). "Mutations or functional defects in TREM2 are closely related to the onset and progression of neurodegenerative diseases." (PMID 37545490, 2023). "Trem2 and Tyrobp are considered as hub genes for microglial functions and the TREM2-APOE pathway has been shown essential to drive the transcriptional phenotype associated with dysfunctional microglia in neurodegenerative diseases." (PMID 37138705, 2023). "Some of these receptors are particularly relevant to disease: TREM2 is a phagocytic receptor mediating microglial phagocytosis of amyloid plaques, synapses, and neurons, and TREM2 variants can confer risk for AD and other neurodegenerative diseases." (PMID 37009452, 2023). "Among these genes, mutated forms of TREM2 represent a pivotal risk factor for this neurodegenerative disease." (PMID 36426369, 2022). "In fact, studies using mouse models of neurodegenerative diseases deficient for TREM2 revealed that TREM2 signalling is essential for microglia to detect and respond to the “neurodegeneration cues”." (PMID 35954208, 2022). "We propose further studies on the molecular mechanisms responsible for loss of TREM2 function and the associations between TREM2 nsSNPs and neurodegenerative diseases." (PMID 35672339, 2022). "Increased levels of soluble TREM2 is associated with worse inflammation and neurodegenerative disease." (PMID 36118688, 2022). "It has received considerable attention based on the linkage of TREM2 variants and dysfunction to a range of neurodegenerative diseases, including Nasu-Hakola and Alzheimer’s disease (AD)." (PMID 36333761, 2022). "According to recent studies, Trem2 plays a pivotal role in the differentiation of microglia into an activated state called damage-associated microglia in various neurodegenerative diseases such as AD and ALS." (PMID 35854340, 2022). "Trem2 expression is a hallmark of microglia in the murine CNS known to limit neurodegenerative diseases by uptake and degradation of amyloid deposition as well as damaged myelin." (PMID 36333761, 2022). "Multiple human heterozygous rare variants in TREM2 have been linked to various neurodegenerative diseases and in particular R47H variant of TREM2 is one of the strongest single allele genetic risk factors that has been associated to AD." (PMID 33652870, 2021).
neurodegenerative disease (continued). "TREM2 is a protective factor for neurodegenerative diseases; moreover, TREM2 mutations are associated with an increased PD risk." (PMID 34594188, 2021). "Recently, among Aβ-associated microglial receptors, triggering receptor expressed on myeloid cells 2 (Trem2) has got attention as a risk factor for several neurodegenerative diseases, including AD." (PMID 34072424, 2021). "The microglia-specific surface receptor TREM2 also binds material associated with neurodegenerative diseases, leading to downstream phagocytosis." (PMID 33924200, 2021). "The previous discovery of AD-related mutations in the microglial expressed genes TREM2 and PLCγ2 has marked them as promising new targets to manipulate microglial function in neurodegenerative disease." (PMID 34615897, 2021). "Within the central nervous system, TREM2 is predominantly expressed by microglia, raising fundamental questions about its role in driving microglia-specific functions associated with neurodegenerative diseases." (PMID 33097708, 2020). "Future studies will be needed to understand which of these mechanisms underlie the risk incurred by loss of TREM2 function before they can be studied as potential therapeutic targets for the treatment of neurodegenerative diseases." (PMID 33097708, 2020). "This biomarker is a soluble form of triggering receptor expressed on myeloid cells 2 (TREM2), a protein implicated in the pathogenesis of neurodegenerative diseases." (PMID 32183348, 2020). "One of the most intensely studied risk factors for neurodegenerative diseases is mutated TREM2, an innate immune receptor expressed by myeloid cells including microglia." (PMID 32765501, 2020). "Beyond the association with neurodegenerative diseases, TREM2 has also been shown to be crucial in brain development." (PMID 33115519, 2020). "Several studies in mouse models for neurodegenerative diseases demonstrated opposing roles of TREM2 deficiency on Aβ and tau pathologies (two pathological hallmarks of AD) with amelioration of amyloid and exacerbation of tau pathology." (PMID 32765501, 2020). "For instance, mutations in TREM2, an immune cells receptor expressed on microglia, represent a risk factor for AD and other neurodegenerative diseases." (PMID 31320450, 2019). "Both CD36 and TREM2 are understood to be neuroprotective; however, in pathological conditions like neuroinflammation, these have been associated with neurodegenerative diseases such as AD." (PMID 31352901, 2019). "The effect that neurodegenerative disease‐linked TREM2 variants have on TREM2 expression and function is discussed, with a particular focus on R47H, one of the best characterised AD‐linked variants." (PMID 30740661, 2019). "Some of these genes, like TREM2, are known to be expressed by microglia and are associated with neurodegenerative diseases." (PMID 31214167, 2019). "We conclude that these iPSC-MGLCs serve as a strong model to study TREM2 and other myeloid genes associated with neurodegenerative disease, including NHD and AD." (PMID 30157425, 2018). "Collectively, these data indicate that microglial activation stages and the RNA signature of specific DAM genes are closely linked to TREM2 in AD and in other neurodegenerative diseases." (PMID 30618585, 2018). "Homozygous mutations in TREM2 cause Nasu-Hakola disease, and rare heterozygous variants are associated with other neurodegenerative diseases such as late-onset AD, frontotemporal dementia, and Parkinson's disease." (PMID 30498474, 2018). "Human genetic studies have demonstrated that triggering receptor expressed in myeloid cells 2 (TREM2) coding variants have a strong association with Alzheimer’s disease (AD) and other neurodegenerative diseases." (PMID 29040522, 2018). "Taken together, these data suggest that TREM2 likely plays a critical role in regulating myeloid cell function within the brain, thereby modulating risk for neurodegenerative diseases." (PMID 29037207, 2017).
neurodegenerative disease (continued). "TREM2 variants have also been assessed as potential risk factors for other neurodegenerative diseases, though the findings in these other disease contexts are less definitive." (PMID 28768545, 2017). "TREM2 variants linked to AD and other neurodegenerative diseases can alter soluble TREM2 generation." (PMID 28768545, 2017). "Genetic variations in the myeloid immune receptor TREM2 are linked to several neurodegenerative diseases." (PMID 27995897, 2016). "Intriguingly, genetic variations in TREM2 are associated with two distinct groups of neurodegenerative diseases." (PMID 27995897, 2016). "In NHD, the mutations are homozygous and the TREM2 is either deleted or misfolded, leading to a complete loss of function, and more serious and early-onset neurodegenerative disease." (PMID 27995897, 2016). "TREM2 variants have also been implicated in the risk for other neurodegenerative diseases such as PD, FTD and ALS." (PMID 26754172, 2016). "Taken together, these results suggest that CSF sTREM2 levels are altered not only in subjects with TREM2 mutations but also in sporadic cases of neurodegenerative diseases." (PMID 26941262, 2016). "In order to understand the molecular basis of how different mutations within TREM2 can lead to distinct neurodegenerative diseases, we performed structural, biophysical, and functional studies of wild-type (WT) and mutant TREM2 proteins." (PMID 27995897, 2016). "The results presented here suggest that the point mutations in TREM2 participate in neurodegenerative disease pathogenesis through distinct molecular mechanisms." (PMID 27995897, 2016). "Here we elucidate how distinct point mutations in TREM2 give rise to different neurodegenerative diseases via two separate loss-of-function mechanisms." (PMID 27995897, 2016). "If this indeed is the case, then TREM2-deficient cell lines and mice would serve as ideal platforms to test how loss of TREM2 impacts pathogenesis under conditions that simulate neurodegenerative disease." (PMID 26337043, 2015). "To date, numerous studies have investigated the genetic link between TREM2 variants and neurodegenerative diseases; however only two studies have empirically tested the functional outcome of these mutations." (PMID 26337043, 2015). "Following this discovery, numerous mutations in TREM2, mostly occurring in exon 2 (IgV domain), have been linked to other forms of neurodegenerative disease." (PMID 26337043, 2015). "This is the first report of an association of TREM2 p.R47H with neurodegenerative diseases other than AD and it is therefore important to consider potential confounding factors." (PMID 23800361, 2013). "Furthermore, TREM2 mutations have been implicated in other neurodegenerative diseases, such as frontotemporal dementia and progressive supranuclear palsy." (PMID 40309835, 2025). "The TREM2 Arg47His (rs759322628) mutation was verified as a strong genetic risk factor associated with AD, which could affect the function of TREM2 protein and could impact neurodegenerative diseases." (PMID 40806186, 2025). "Furthermore, the loss‐of‐function (LoF) mutations in TREM2 play an important role in neurodegenerative diseases, particularly AD." (PMID 41476737, 2025). "Recent studies indicate that Trem2 expression in astrocytes may be linked to the pathological processes in neurodegenerative diseases, including AD." (PMID 40205810, 2025). "Understanding how genetic variants affect TREM2 structure and function is critical for elucidating the mechanisms underlying neurodegenerative diseases and may provide valuable insights for potential therapeutic strategies." (PMID 40247363, 2025). "Summary of TREM2 genetic variants in neurodegenerative diseases." (PMID 40940798, 2025). "Furthermore, apolipoprotein E (APOE) and TREM2, known to be neurodegenerative disease risk genes, are enriched in microglia purified by the adult human brain." (PMID 39456734, 2024).
neurodegenerative disease (continued). "Thus, understanding the function and regulation of TREM2, including in the context of the R47H mutation, is crucial for developing therapeutic strategies for both aging-related neurodegenerative diseases and HIV-associated neurocognitive impairment." (PMID 39459844, 2024). "Mutations in both DAP12 and TREM2 have been linked to neurodegenerative diseases." (PMID 39008111, 2024). "Given the fact that the R47H TREM2 variant has been associated with several neurodegenerative diseases, we have also focused on how this variant may be more permissive of damage exerted on the brain by the relevant pathology, in this case plaques." (PMID 36803190, 2023). "Despite numerous studies suggesting that TREM2 plays a significant role in the pathogenesis of neurodegenerative diseases, the exact mechanisms and causative relationships between TREM2 and these diseases remain unclear." (PMID 38020891, 2023). "Intriguingly, different neurodegenerative diseases are associated with distinct TREM2 variations." (PMID 37433768, 2023). "In addition, mutations in TREM2 have been identified as risk factors for several neurodegenerative diseases, including PD." (PMID 35890306, 2022). "Furthermore, the study provides new information on the dynamics of CDR regulations in wild-type TREM2 and its deleterious variants, and thus, provides clues regarding drug design and TREM2 gene therapy for the treatment of neurodegenerative diseases." (PMID 35672339, 2022). "Triggering Receptor Expressed on Myeloid Cells 2 is associated with neurodegenerative diseases." (PMID 34867158, 2021). "TREM2 has an effect on increasing myeloid cell number in response to inflammation or disease; therefore, TREM2 deficiency is associated to a decrease of activated myeloid cells clustering in AD and to neurodegenerative diseases." (PMID 33652870, 2021). "Q9NZC2 is encoded by TREM2, which has been reported to be associated with many neurodegenerative diseases such as Behavioral variant of frontotemporal dementia, Early-onset autosomal dominant Alzheimer disease, Progressive non-fluent aphasia, Semantic dementia." (PMID 32626709, 2020). "Interestingly, microglial TREM2, implicated in risk for neurodegenerative diseases, is required for microglia to signal to astrocytes to limit their synapse uptake." (PMID 32765501, 2020). "Dynamical scenarios, as provided by the present study, may be critical to our understanding of the roles of these TREM2 mutations in neurodegenerative diseases." (PMID 32107424, 2020). "TREM2 mutations have recently been associated with AD and some other neurodegenerative diseases." (PMID 32826884, 2020). "Interestingly, the expression levels of TREM2, a cell surface receptor exclusively expressed on microglia in the brain and implicated in neurodegenerative diseases, were positively correlated with the exacerbation of brain inflammation." (PMID 32183348, 2020). "The deficiency of TREM2 could affect the microglia function, aggravate the β amyloid and cause α-synuclein overexpression in neurodegenerative disease." (PMID 33014520, 2020). "Pathogenic TREM2 variants of different effects are found in several neurodegenerative diseases." (PMID 33101276, 2020). "The importance of TREM2 in the central nervous system (CNS) is widely recognized, as TREM2 mutations are linked to an increased risk of developing several neurodegenerative diseases, and TREM2 RNA has been found to be upregulated in the brain of patients and mouse models." (PMID 31551688, 2019). "In particular, more detailed data regarding how neurodegenerative disease–associated variants in TREM2 affect its structure and dynamics, and in turn its ability to bind ligands, would enable development of more precise therapeutics to target TREM2 in neurodegenerative disease." (PMID 32021611, 2019). "In addition, in vitro conditions cause a reduced expression of microglial genes associated with different neurodegenerative diseases, e.g., TREM2, in human microglia." (PMID 30108586, 2018).